JAK1 (Janus kinase 1)
Diseases named in the same sentence as JAK1 in open-access papers (continued):
Sharing a sentence is not in itself a finding about the gene and the disease.
non-small cell lung carcinoma (14 papers, 2015 to 2025). A group of at least three distinct histological types of lung cancer, including non-small cell squamous cell carcinoma, adenocarcinoma, and large cell carcinoma. "In non-small-cell lung cancer, IL-10 derived from M2 macrophages promotes cancer stemness through the JAK1/STAT1/NF-κB/Notch1 pathway." (PMID 36838713, 2023). "In the studies dedicated to non-small cell lung cancer, IL-10 upregulated Janus kinase 1 (JAK1) signaling, which also supported tumor growth." (PMID 36613838, 2022). "Tumorigenesis-associated pathways, such as the ERBB signaling pathway, MAPK signaling pathway, Toll-like receptor signaling pathway, and non-small cell lung cancer, were also predicted in the high JAK1 expression group." (PMID 33323549, 2020). "In gefitinib-resistant non-small-cell lung cancer, IL-6R/JAK1/STAT3 signaling activation leads to de novo resistance to irreversible EGFR inhibitors." (PMID 27861147, 2017). "Furthermore, the inhibition of JAK1 with Anwulignan effectively suppresses the growth of non-small cell lung cancer by targeting the JAK1/STAT3 signaling pathway." (PMID 38921583, 2024). "In addition, TAM-derived IL-10 promotes cancer stem cell (CSC)-like characteristics of non-small cell lung cancer (NSCLC) cells through JAK1/STAT1/NF-κB/Notch1 signaling." (PMID 34722637, 2021). "In non-small cell lung cancer (NSCLC), secretion of oncostatin-M (OSM), a member of the IL-6 cytokine family, by cancer-associated fibroblasts increases STAT3 activity through activation of JAK1 and is a possible mechanism of resistance to targeted therapy such as EGFR and MEK inhibitors." (PMID 33521321, 2020). "For example, a low level of IFN-γ stimulates CSC properties in non-small cell lung cancer (NSCLC) cells; however, a high concentration of IFN-γ induces apoptosis through the JAK1/STAT1/caspase pathway." (PMID 35455671, 2022). "Ruxolitinib, a selective JAK1/2 inhibitor, enhances replication and efficacy of VSV-IFN-β and VSV-ΔM51 in non-small cell lung cancer (NSCLC) and human PDACs, respectively, by inhibiting STAT1/2 phosphorylation and reducing antiviral responses that restrict viral replication." (PMID 40927720, 2025). "Moreover, JAK1/2 inhibitors, namely AZD1480 for the treatment of solid tumors and Momelotinib that treats non-small cell lung cancer, resulted in clinical trial termination due to neurotoxicity and neutropenia, respectively [NCT01112397, NCT02206763]." (PMID 37305676, 2023).
Sepsis (14 papers, 2021 to 2026). Sepsis is defined as life-threatening organ dysfunction caused by a dysregulated host response to infection. "ZJF reversed the lung injury caused by sepsis through inhibiting JAK1/STAT3 expression and subsequently reducing inflammatory mediator production." (PMID 33506010, 2021). "As IL-6 is also known as a key inflammatory mediator during cytokine storm in sepsis, further investigation of a possible impact of Ruxolitinib, JAK1 and IL-6 in RNase1-associated EC dysfunction might be of future interest." (PMID 37189117, 2023). "Therefore, ZJF reversed sepsis caused lung injury by downregulating the expression of JAK1/STAT3-related proteins." (PMID 33506010, 2021). "In summary, PRMT5 regulates sepsis-induced lung injury through a methylation-dependent JAK1/STAT3 pathway, serving as a potential target for clinical intervention." (PMID 41568710, 2026). "This study confirms established infection risks of JAK-1 inhibitors in AD (particularly herpes zoster) and identifies novel potential safety signals (sepsis, appendicitis, and septic shock)." (PMID 41255603, 2025). "In a model of sepsis caused by cecal ligation and puncture, emodin protected the jejunum in rats with sepsis by activating JAK1/STAT3 signaling pathway and regulates apoptosis proteins (Bcl-2 and Bax) expression." (PMID 35744949, 2022). "We consider that GDF15 plays a protective role in sepsis; it can inhibit the M1 polarization of macrophages as well as the phosphorylation of JAK1/STAT3 signaling pathway and nuclear translocation of NF-κB p65 to alleviate inflammation." (PMID 34566964, 2021). "Our study not only evaluated the therapeutic effect of ZJF on lung injury induced by sepsis but also provided a new perspective for resolving the mechanism of ZJF in regulating the JAK1/STAT3 signaling pathway." (PMID 33506010, 2021). "It remains to be elucidated whether JAK1/2 inhibitors may be useful as a treatment option during the course of sepsis." (PMID 39403371, 2024). "In summary, our study found that GDF15 has good clinical application value in sepsis and plays a protective role in the development of sepsis by regulating the functions of macrophages and inhibiting the activation of JAK1/STAT3 pathway and nuclear translocation of NF-κB p65." (PMID 34566964, 2021). "Therefore, downregulating the JAK1/STAT3 signaling pathways was a potential avenue of ZJF in reversing lung injury induced by sepsis." (PMID 33506010, 2021). "We found that IRF7 might be stimulated by the IFN-β/JAK1/STAT3 pathway in polymicrobial sepsis." (PMID 41212050, 2025). "Pharmacological manipulation of the JAK1/2-STAT1 pathway and an LPS-induced murine sepsis model were used for mechanistic and therapeutic validation." (PMID 41463524, 2025). "Animal experiments have revealed that, during sepsis, myeloid-related protein 8/14 (MRP8/14) induces sustained IP10 production through the IFN-β-JAK1/TYK2-STAT1-IRF7 pathway." (PMID 39045132, 2024). "The volcano plot and heatmap indicated that JAK3, CHMP5 and IFNAR1 were upregulated while CASP8, VDAC2, FASLG, JAK1, STAT4 and BCL2 were downregulated in sepsis." (PMID 38894720, 2024). "Sepsis induced JAK1 phosphorylation, followed by STAT3 phosphorylation, which activated the JAK1/STAT3 signaling pathway." (PMID 33506010, 2021). "In recent years, JAK1/STAT3 signaling pathway has attracted more and more attention in the regulation of inflammatory response in sepsis." (PMID 34566964, 2021). "In recent years, the significance of JAK1/STAT3 signaling involved in regulating inflammation and injury of sepsis attracted more attention due to its simple and effective activation." (PMID 33506010, 2021). "This study provides new insights into the signaling pathways that induce MHC class II expression in neutrophils, highlighting the potential for therapeutic targeting of JAK1/2 signaling in the treatment of gram-negative bacteremia and sepsis." (PMID 39403371, 2024).
Sepsis (continued). "Our findings shed new light on the critical role of the IFNβ-JAK1/TYK2-STAT1-IRF7 pathway in MRP8/14-induced IP-10 expression in the progression of endotoxemia, which may provide new therapeutic strategies for sepsis." (PMID 37701855, 2023). "Thus, we elucidated the role of the JAK1/2-STAT1 pathway in taurine-mediated metabolic reprogramming and IL-1β suppression in M1 macrophages and evaluated taurine’s therapeutic potential in a murine model of LPS-induced sepsis." (PMID 41463524, 2025). "At the same time, GDF15 could alleviate the inflammatory response by regulating the function of macrophages and reducing the phosphorylation of JAK1/STAT3 and the nuclear translocation of NF-κB p65, which confirmed that GDF15 played a protective role in sepsis from the cellular level." (PMID 34566964, 2021).
acute GVHD (13 papers, 2016 to 2025). "Itacitinib is a JAK1 inhibitor that is being investigated for the treatment of acute graft-versus-host disease." (PMID 38731900, 2024). "Ruxolitinib, a balanced JAK1/JAK2 inhibitor with similar specificity to baricitinib has been approved for the treatment of steroid refractory acute GVHD and chronic GVHD." (PMID 37744381, 2023). "This asserts that the anti-inflammatory effects of BRD4 inhibition are independent of STAT1, which is a target of the currently FDA approved Jak1/2 inhibitor, ruxolitinib, for steroid refractory acute GVHD." (PMID 34722316, 2021). "In a noncancer but immune-related setting, JAK1 signaling has been implicated in the immune response in acute GVHD, and treatment with itacitinib demonstrated clinical benefit in a phase I study." (PMID 38115208, 2023). "Ruxolitinib, an oral selective JAK1/2 inhibitor, received FDA approval for the treatment of steroid-refractory acute GVHD in 2019 and remains the only agent approved for acute GVHD." (PMID 35443042, 2022). "The JAK1/JAK2 inhibitor ruxolitinib was approved by the US Food and Drug Administration for the treatment of steroid-refractory acute GVHD in mid-2019." (PMID 35908108, 2022). "A recent phase III clinical trial indicated that ruxolitinib treatment, a selective Janus kinase (JAK1 and JAK2) inhibitor, significantly improved glucocorticoid refractory acute GVHD." (PMID 36052066, 2022). "Ruxolitinib, a JAK1/2 inhibitor reduces the number of circulating activated T cells in patients with cGVHD, was prospectively evaluated in a phase III randomized study including children who had glucocorticoid-refractory acute GVHD after HSCT." (PMID 36983151, 2023).
diabetes (13 papers, 2015 to 2026). "This study provides preclinical validation for repurposing JAK1/JAK2 inhibitors to mitigate checkpoint inhibitor-associated diabetes while preserving anticancer immunity." (PMID 40534861, 2025). "This anecdotal evidence comes from a case report of a 15 year old boy with diabetes caused by a gain of function STAT1 mutation who was given Ruxolitinib (a JAK1/JAK2 inhibitor) to treat additional symptoms of this disorder including chronic candidiasis and autoimmune enteropathy." (PMID 37867531, 2023). "Therefore, we set out to test whether the effect of ABT 317 on common γ chain cytokine signaling could explain the difference between effects of IFN-γ/IFNγR deficiency and JAK1 inhibition on diabetes in NOD mice." (PMID 33343569, 2020). "In NOD mice with anti–PD-L1–induced hyperglycemia, administration of a JAK1/JAK2 inhibitor resulted in the reversal of diabetes." (PMID 40534861, 2025). "In NOD mice, twice-daily ABT-317 (a JAK1-selective inhibitor) for 40 days reversed diabetes in 94% of new-onset cases, with 44% sustaining normoglycemia 60 days post-treatment." (PMID 40534861, 2025). "The JAK/STAT pathway is essential for the biological function of various cytokines and growth factors, the potential adverse effect of JAK1 inhibition on diabetes is an important consideration." (PMID 34769307, 2021). "In terms of diabetic complications, a JAK1 inhibitor baracitinib has been shown to protect the kidney from T2DM-induced albuminuria, highlighting a role for JAK1 in diabetes-induced vascular barrier dysfunction." (PMID 34769307, 2021). "Dysfunction in the JAK–STAT signaling pathway has been implicated in the pathogenesis of various metabolic diseases, including metabolic syndrome and diabetes, and the JAK1/2 inhibitor baricitinib was shown to preserve β-cell function in a phase 2 clinical trial for stage 3 diabetes." (PMID 41306972, 2025). "Our pre-clinical data show that inhibitors of JAK1/JAK2 prevent diabetes and reverse newly diagnosed diabetes in the non-obese diabetic (NOD) mouse model of T1D." (PMID 35606820, 2022). "Notably, the JAK1/2 inhibitor AZD1480 was effective in preventing insulitis in NOD mice, it prevented HLA-I hyperexpression on their islets and crucially reduced the incidence of spontaneous diabetes." (PMID 37867531, 2023). "Treatment with AZD1480 (a JAK1/JAK2 inhibitor) and ABT 317 (a JAK1-selective inhibitor) protected non-obese diabetic mice against autoimmune diabetes and reversed diabetes in newly diagnosed non-obese diabetic mice." (PMID 37854597, 2023). "Our pre-clinical data show that inhibitors of JAK1/JAK2 prevent diabetes and reverse newly diagnosed diabetes in the T1D non-obese diabetic mouse model." (PMID 35606820, 2022).
eosinophilia (13 papers, 2017 to 2025). "JAK1 is a known AEI gene 55,56, and mutations in JAK1 cause autosomal dominant autoinflammation, immune dysregulation, and eosinophilia (AIIDE)." (PMID 40894531, 2025). "Germline gain-of-function (GOF) variants in JAK1 are a cause of severe atopy and eosinophilia." (PMID 36546480, 2022). "JAK inhibitors such as ruxolitinib demonstrate significant efficacy in JAK1/2-mutant eosinophilia by suppressing constitutive signaling pathway activation." (PMID 41141324, 2025). "Another significant finding is the JAK1 R629_S632delinsA mutation in the pseudokinase domain, which confers growth factor independence through persistent JAK-STAT activation and demonstrates responsiveness to ruxolitinib in clonal eosinophilia." (PMID 41141324, 2025). "Inhibition of JAK1 should be used with caution, as a phase II clinical trial on solcitinib (a selective JAK1 inhibitor) (NCT01777256) was discontinued because of severe drug reaction with eosinophilia and systemic symptoms (DRESS) syndrome and hepatic function abnormalities." (PMID 32789005, 2020). "Therefore, it seems that regardless of the particular variant, JAK1-activating mutations result in superficial inflammatory lesions and eosinophilia associated with internal organ involvement (particularly the gastrointestinal tract)." (PMID 38103162, 2023). "In addition to IFN and IL pathways known to signal through the JAK/STAT pathway, Reactome analysis revealed enrichment of leukotriene/eoxin and IL-33 signaling, suggesting unexpected mechanisms by which enhanced JAK1 signaling may drive allergic inflammation and eosinophilia." (PMID 36546480, 2022).
Immunodeficiency (13 papers, 2016 to 2025). Failure of the immune system to protect the body adequately from infection, due to the absence or insufficiency of some component process or substance. "In summary, we identified that loss of JAK1 in NK cells drives innate immune deficiency, whereas JAK2 deficiency leaves NK cell numbers and maturation unaltered." (PMID 30671064, 2018). "The clinical phenotype was characterized by immunodeficiency plus aggressive urothelial carcinoma that was fatal in the third decade of life, suggesting that impaired JAK1 function may be a predisposing factor for urothelial carcinoma." (PMID 31552026, 2019). "Exome sequencing revealed two homozygous hypomorphic mutations affecting the pseudo-kinase domain of JAK1 leading to impaired phosphorylation of several STAT proteins (STAT1, STAT3, STAT4, STAT5, and STAT6), which contributed to the immunodeficiency manifested by the patient." (PMID 41438753, 2025). "In the context of the JAK/STAT pathway, WES allows for the discovery of rare or de novo mutations in coding regions of genes such as JAK1-3, TYK2, and STAT1-6, which may be implicated in immunodeficiencies, autoimmune syndromes, or hematological disorders." (PMID 41438753, 2025). "This statement suggests that the activation of receptor complex {IL7R, IL2RG} may activate {JAK1, JAK3} to cause immunodeficiency disease." (PMID 27819359, 2016). "Moreover, further chemical engineering and pharmaceutical formulation of the JAK1 siRNA could expand its scope of use for the treatment of immune disorders beyond the skin." (PMID 37925520, 2023). "have utilized siRNA to target Janus kinase 1 (JAK1) in various species, illustrating that the dysregulation of JAK1 plays a role in numerous immune disorders." (PMID 39897639, 2025).
dermatitis (12 papers, 2019 to 2026). An inflammatory process affecting the skin. "In this study, using global lipidome profiling, we unveiled the dysregulated sphingolipid metabolism observed during dermatitis progression caused by the constitutive activation of Jak1." (PMID 36639058, 2023). "These alterations illustrate the potentially novel pathogenic function of Jak1-dependent dermatitis pathology." (PMID 36639058, 2023). "Moreover, mice harboring a point mutation leading to JAK1-specific hyperactivation develop spontaneous skin barrier disruption and a dermatitis phenotype." (PMID 31649667, 2019). "Here, we performed untargeted and targeted lipidomic analyses of an AD-like dermatitis model resulting from constitutive activation of Janus kinase 1 (Spade mice) to capture the comprehensive lipidome profile during dermatitis onset and progression." (PMID 36639058, 2023). "We used a mouse model of Jak1 activity-dependent dermatitis to understand the pathogenesis of dermatitis at the molecular level." (PMID 36639058, 2023). "Generation of bone marrow chimeras revealed that Jak1 expression in non-hematopoietic cells was responsible for the development of dermatitis, but Jak1 acting in immune cells exacerbated the dermatitis symptoms and disease severity." (PMID 31447854, 2019). "Hh also reduced expression of other genes for inflammatory signaling pathways implicated in skin inflammation including TNFR (Tnfrsf25), JAK-STAT (Jak1), and NF-κB (Trl4, Myd88, Cd69, Cd48, Irf1)." (PMID 31264977, 2019). "Thus, this is the first report showing dysregulated ceramide metabolism via constitutive activation of Jak1 in progressive dermatitis in mice." (PMID 36639058, 2023). "PA-IL-32-AD-model was further subjected to different treatment in vivo, results of which showed that sh-JAK1 or miR-155 inhibitor effectively alleviated the development of specific dermatitis in PA-IL-32-AD-model, based on the skin inflammation clinical scores." (PMID 35545774, 2022). "Treatment with a selective JAK1 inhibitor upadacitinib at a dose of 15 mg/day improved the patient’s pruritis and dermatitis (although to a lesser extent than the benefits her sons experienced with ruxolitinib); however, it was associated with side effects of rosacea and weight gain." (PMID 36546480, 2022). "Correlations were also calculated between the severity of dermatitis (CADESI scores) and semiquantitative measurements of the intensity of scoring for JAK1 and JAK3." (PMID 37624299, 2023). "Similarly, tofacitinib (JAK1/3) and oclacitinib (JAK1) inhibited the production of proinflammatory Th2 cytokines, including IL-4, in the toluene-2,4-diisocyanate (TDI) dermatitis model." (PMID 31649667, 2019). "In AD, excessive activation of JAK1 induces the phosphorylation of STAT proteins, the hyperproliferation of keratinocytes, and the secretion of proinflammatory cytokines, leading to skin barrier disruption, the progression of pruritus and dermatitis symptoms, and pain." (PMID 40429704, 2025). "Selective JAK1 inhibition is a promising therapeutic strategy for attenuating m-alloknesis and improving quality of life for patients with AD, independent of general skin inflammation and barrier function." (PMID 41301837, 2025). "Notably, the results of this study show that even a single dose of the JAK1 inhibitor resulted in a rapid and marked reduction in m-alloknesis in the AD model but did not markedly attenuate skin inflammation or improve barrier function." (PMID 41301837, 2025). "Inhibition of Jak1 and Jak2 by topically applied ruxolitinib or momelotinib successfully decreased inflammation in a hapten-induced hypersensitivity model as well as in TSLP-induced dermatitis in mice together with the down-regulation of mRNA expression of IL-4, IL-5, IFNγ, and TSLP in the skin." (PMID 31447854, 2019).
Crohn disease (11 papers, 2021 to 2025). A gastrointestinal disorder characterized by chronic inflammation involving all layers of the intestinal wall, noncaseating granulomas affecting the intestinal wall and regional lymph nodes, and transmural fibrosis. "Upadacitinib, an oral JAK1 inhibitor, has demonstrated efficacy in treating Crohn's disease during phase III clinical trials." (PMID 36968986, 2023). "JAK1 inhibitors are currently undergoing investigation as potential therapies for Crohn's disease." (PMID 36968986, 2023). "Upadacitinib is a Janus kinase-1 (JAK-1) selective inhibitor, recently approved for the treatment of moderate-to-severe Crohn’s disease, with good efficacy and safety data in both induction (U-EXCEL and U-EXCEED studies) and the maintenance of remission (U-ENDURE study)." (PMID 40710828, 2025).